ENSG00000238694
Synonyms: LOC124900893
Gene: Small nucleolar RNA gene on chromosome 4 (34,966,241 to 34,966,344, reverse strand). Ensembl gene ENSG00000238694.
Gene Ontology:
Biological process: RNA processing
Cellular component: nucleolus
Homologues: Paralogues in human: SNORD13 (87% identical), SNORD13D (86% identical), SNORD13E (85% identical), SNORD13P1 (84% identical), SNORD13P3 (83% identical).